ITGB1 (integrin subunit beta 1)
Diseases named in the same sentence as ITGB1 in open-access papers (continued):
Sharing a sentence is not in itself a finding about the gene and the disease.
lung cancer (33 papers, 2012 to 2025). A malignant neoplasm involving the lung. "High expression of ITGB1 has been found in lung cancer stem cells, and studies indicate that the binding of ITGB1 to collagen promotes the expansion and generation of CSCs, thereby enriching tumor stem cells in lung cancer." (PMID 39239559, 2024). "Gene array and bioinformatics analyses implied that ITGB1 protein expression levels were higher in lung cancer patients." (PMID 37925496, 2023). "We confirmed that CD44 and ITGB1 are PI4K2A-associated proteins and that SPP1 binds to CD44 and ITGB1 in mesenchymal lung cancer cells." (PMID 36757799, 2023). "KDM5A is overexpressed in lung cancer tissues and facilitates cell proliferation, invasion, and metastasis of lung cancer via inhibiting the expression of p27 and upregulating cyclin D1, and ITGB1." (PMID 33596982, 2021). "It has been shown that the inhibition of ITGB1 in vitro and in vivo can decrease lung cancer invasion and metastasis." (PMID 31217907, 2019). "In 27 paired of NSCLC samples, ITGB1 was highly expressed in lung cancer relative to non tumor samples via qRT-PCR analysis (FC = 3.24, P = 0.002)." (PMID 28537888, 2017). "ITGB1, as a direct target of miR-134, was reported to promote the occurrence and metastasis of lung cancer." (PMID 28537888, 2017). "Similarly, in lung cancer, curcumin modulates the circ-PRKCA/miR-384/ITGB1 pathway, suppressing the malignancy of lung carcinoma." (PMID 36143462, 2022). "Additionally, overexpression of a H3K4 histone demethylase, Jumonji, AT Rich Interactive Domain 1A (JARID1A) leads to the activation of cyclin D1/E1 and Integrin Subunit Beta 1 (ITGB1) expression, promoting lung cancer cell growth and metastasis." (PMID 33803458, 2021). "The increased expression of Itgb1 is correlated with poor prognosis in lung cancers." (PMID 33865415, 2021). "ITGB1 was an important beta subset, because it could regulate cell migration and was regarded as a prometastatic gene for lung cancer." (PMID 32140187, 2020). "The authors reported that osteopontin, LAMB3 and ITGB1 are pro-metastatic genes for lung cancer." (PMID 28871224, 2017). "ITGB1 was identified as an independent prognostic integrin marker associated with OS in NSCLC, which provided important clues to understanding the molecular mechanism of metastasis and contributing to the therapeutic treatment of lung cancer." (PMID 28537888, 2017). "In lung cancer (LC), ZEB1 decreases nuclear HDAC4 accumulation and promotes ITGB1 transcription, whereas RBP2 directly controls ITGB1 transcription." (PMID 38279122, 2024). "Previous studies have shown that the activation of ITGB1/FAK pathway signal can promote EMT and angiogenesis in lung cancer, liver cancer and non-small cell lung cancer." (PMID 34095137, 2021). "In lung cancer, silencing of NFIX induced a decrease in IL6ST, TIMP1, and ITGB1 gene expression and reduced cell proliferation, migration, and invasion processes." (PMID 31766658, 2019). "CXCL12 was shown to increase the migration of lung cancer cells through the CXCR4-mediated activation of ERK, which in turn activates IKKa/b and NF-κB, resulting in the activations of integrins (ITGB1 and ITGB3)." (PMID 23322021, 2013). "ITGB1 and RRAS were highly expressed in all of the renal and most of the lung cancer cell lines, and both genes were expressed at relatively low or undetectable levels in all of the leukemia and most of the melanoma cell lines." (PMID 22570691, 2012). "ITGB1 and DRAM1 were also abnormally expressed in many types of cancer including lung cancer." (PMID 35529878, 2022). "Of these proteins, HSP90AA1, ITGB1, cytokeratin-8 (KRT8) and receptor for activated C-kinase (RACK1) are identified prognostic markers for overall survival in solid malignancies including lung cancer." (PMID 33777753, 2021). "Lymphatic metastasis in lung cancer has a high concentration of ITGB1 as compared to non-lymphatic metastasis." (PMID 28871224, 2017).
lung cancer (continued). "Hence, NFIX with IL6ST, TIMP1, ITGB1, PTCH1, GGCX and NFAT5 genes may regulate the migration and invasion process and they could serve as potential therapeutic targets in patients with lung cancer to predict survival and improve prognosis." (PMID 28871224, 2017).
glioma (32 papers, 2013 to 2025). A benign or malignant brain and spinal cord tumor that arises from glial cells (astrocytes, oligodendrocytes, ependymal cells). "The effect of ITGB1 expression on glioma proliferation and the association between ITGB1 and Notch signaling pathway were further explored." (PMID 33014056, 2020). "CD9 regulated glioma progression via calcium signaling and synaptic pathways, interacting with ITGB1 and CD81." (PMID 40406701, 2025). "There are many well-studied pathogenic genes and regulators of gliomas, including IDH1/2, 1p/19q codeletion, integrin β1 (ITGB1) and v-raf murine sarcoma viral oncogene homolog B1 (BRAF) V600E mutation." (PMID 34722629, 2021). "In particular, ITGB1 encodes the β1 subunit of extracellular matrix (ECM) integrins and shows reduced expression in gliomas compared with normal controls." (PMID 34722629, 2021). "Among these, connective tissue growth factor (CTGF) plays an auxiliary role in gliomas by activating the ITGB1-TrkA-NF-kB pathway, which can inhibit E-cadherin at the transcription level and enhance the invasion and migration of glioma cells." (PMID 34659360, 2021). "The expression of ITGB1 in glioma tissues was significantly higher than that in adjacent normal tissues and was negatively correlated with the survival time of patients." (PMID 33014056, 2020). "ITGB1 can significantly promote the proliferation of glioma cells via feedback regulation of the Notch signaling pathway." (PMID 33014056, 2020). "The mRNA and protein expression of ITGB1 in glioma tumor samples was significantly higher than that in tumor adjacent normal tissue samples (p < 0.05)." (PMID 33014056, 2020). "It has been reported that SPP1/CD44 signaling in the glioma perivascular niche promotes aggressive tumor growth, and ITGB1 was related to the dismal OS in NSCLC." (PMID 33324676, 2020). "The relationship between ITGB1 expression in glioma tissues and their prognosis was analyzed in clinical samples." (PMID 33014056, 2020). "Integrin beta 1 (ITGB1) mRNA and protein levels in clinical glioma tumor samples and tumor adjacent normal tissue samples were analyzed using quantitative real-time PCR and immunohistochemistry, respectively." (PMID 33014056, 2020). "High proliferation and strong invasiveness are important reasons for the poor prognosis of glioma, and ITGB1 is often expressed abnormally in cancer and correlates with malignant tumor phenotypes, such as invasion, migration, angiogenesis, and proliferation." (PMID 33014056, 2020). "The proliferation rate was significantly higher in ITGB1 overexpression glioma cells than that in the control group from the fourth day to the sixth day (p=0.018)." (PMID 33014056, 2020). "The result indicated that the expression level of ITGB1 in glioma tumor tissues is significantly higher than that in the normal tissue." (PMID 33014056, 2020). "The reliability of ITGB1 as a potential biomarker was further explored, and the relationship between ITGB1 expression and prognosis of 43 glioma patients was analyzed." (PMID 33014056, 2020). "ITGB1 expression in glioma tissues was significantly higher than that in adjacent normal tissues and was negatively correlated with the survival time of patients." (PMID 33014056, 2020). "In this study, ITGB1 was shown as one of the most important genes related to the Notch signaling pathway in glioma, affecting the expression of the other genes." (PMID 33014056, 2020). "The clone formation assay further verified the effects of ITGB1 on the proliferation of glioma cells." (PMID 33014056, 2020). "The ITGB1 expression levels in the glioma tissues of the 43 patients were investigated by qRT-PCR (data not shown)." (PMID 33014056, 2020). "The relationship between ITGB1 expression level and glioma prognosis was analyzed in the 43 patients." (PMID 33014056, 2020). "The ITGB1 expression levels were firstly detected in five glioma cell lines, U87, U251, U373, SHG44, and T98 G using qRT-PCR." (PMID 33014056, 2020).
glioma (continued). "The expression level of ITGB1 protein in gliomas was significantly higher than the expression level in adjacent normal tissue (p value = 0.014)." (PMID 33014056, 2020). "It was found that the patients with low ITGB1 expression had longer survival time than those with high ITGB1 expression, suggesting that ITGB1 was negatively correlated with the prognosis of glioma." (PMID 33014056, 2020). "The relationship between ITGB1 expression and the prognosis of patients with gliomas was analyzed using the Kaplan-Meier curve." (PMID 33014056, 2020). "qRT-PCR revealed that the average mRNA expression levels of ITGB1 in glioma samples were significantly higher than those in the peritumoral normal tissues (p value = 0.0022)." (PMID 33014056, 2020). "There are also reports suggesting important roles of ITGB1 in glioma invasiveness and resistance to temozolomide treatment, which are in accordance with our findings." (PMID 24358143, 2013). "It has been reported to inhibit glioma progression by suppressing ITGB1/FAK signaling." (PMID 36589752, 2022). "The mechanism of how ITGB1 functioned in glioma was explored in this study." (PMID 33014056, 2020). "To test this hypothesis, we altered the expression level of ITGB1 by interference and overexpression and examined the proliferation and colony formation ability of glioma cells." (PMID 33014056, 2020). "The high expression level of ITGB1 in glioma tumor tissues and its correlation with the clinical prognosis indicated that ITGB1 might play an important role in the development of glioma tumor and suggested ITGB1 to be a potential marker for glioma prognosis." (PMID 33014056, 2020). "Therefore, ITGB1 can significantly promote proliferation of glioma cells via feedback regulation of the Notch signaling pathway." (PMID 33014056, 2020). "However, as a prognostic indicator, the relevance and clinical significance of ITGB1 and glioma are rarely mentioned." (PMID 33014056, 2020). "CTGF was also found to play a prominent role in glioma cell invasion by activating ITGB1-TrkA-NFkB axis, wherein it resulted in the activation of ZEB-1 (a transcriptional repressor), which subsequently brought down the levels of e-cadherin and thereby enhanced migration and invasion." (PMID 27291091, 2016). "Additionally, the top Kyoto Encyclopedia of Genes and Genomes (KEGG) pathways associated with COL1A1, ITGB1, THY1, and PDGFRA genes included pathways such as “ECM receptor interaction, leukocyte transendothelial migration, platelet activation, focal adhesion, and glioma” among others." (PMID 40817072, 2025). "In MAN1C1-expressing glioma cells, the presence of highly glycosylated receptors, such as CD44 and integrins (ITGB1, ITGAV, ITGA8, ITGAB1) facilitates this interaction." (PMID 39333557, 2024). "Correlation analysis revealed that TSPAN4 was positively correlated with ITGB1, GDF15, ITGA3 and ITGA6, and negatively correlated with CHD7, ASPDH, TMEM8B and GHITM in glioma." (PMID 39723210, 2024). "A total of 18 genes were significantly negatively correlated with DGCR5, including GNAI3, VIM, ITGB1, HIF1A, and HDAC1, all of which are critical factors affecting glioma development." (PMID 33085646, 2020). "Therefore, we speculated that ITGB1 might affect the proliferation of glioma." (PMID 33014056, 2020). "Additionally, glioma cluster 2 cells expressed selectins (LGALS1 and LGALS3), integrins (ITGB1), and glycosylation targets (VIM, TIMP1, HIF1A, and CD44)." (PMID 39333557, 2024). "MES-like glioma cells expressed multiple receptors for ANGPTL4, including SDC2 SDC3, SDC4, and integrins ITGA5 and ITGB1, suggesting that the ANGPTL pathway may be responsible for the enrichment of GSCs in ECMhi tumors." (PMID 37884531, 2023).
glioma (continued). "The quantitative real-time PCR method was used to evaluate mRNA expression of SEMA3(A-G), neuropilins (NRP1 and NRP2), plexins (PLXNA2 and PLXND1), cadherins (CDH1 and CDH2), integrins (ITGB1, ITGB3, ITGA5, and ITGAV), VEGFA and KDR genes in 59 II-IV grade glioma tissues." (PMID 33036421, 2020). "Finally, by using gene correlation analysis, we found that the COL1A1, COL1A2, FN1, ITGA1, ITGB1, and ANXA1 genes may play a synergistic role in glioma patients." (PMID 35711921, 2022). "Furthermore, C6S-p treatment also resulted in the suppression of ITGB1 mRNA expression in glioma cells as compared to non-treated glioma cells, which is consistent with the effects of CHSY1 silencing using specific siRNAs." (PMID 34944101, 2021).
melanoma (29 papers, 2012 to 2025). A malignant, usually aggressive tumor composed of atypical, neoplastic melanocytes. "miR-183, downregulated in melanoma, targets integrin subunit beta 1 (ITGB1) which is associated with tumor growth, metastasis and drug resistance, and miR-22 inhibits the expression of EMT-promoting MMP14 and Snail transcription factors." (PMID 34638331, 2021). "Secreted fibronectin regulates ITGAV (Integrin subunit alpha V) and ITGB1 (Integrin beta-1) expression, globally promoting melanoma cell adhesion and migration." (PMID 33800394, 2021). "Our results show that FOS, NR4A, and ITGB1 genes were significantly higher in older melanoma patients with tumor-positive SLNs." (PMID 33373316, 2020). "These analyses show that FOS, NR4A, and ITGB1 genes were significantly higher in older melanoma patients with positive SLNs." (PMID 33373316, 2020). "We also found an intense positive correlation between MALAT1 and ITGB1 levels (r = 0.581, P < 0.001) in melanoma tissues." (PMID 27966454, 2017). "We further explored the effects of miR-183 on the ITGB1 expression and its downstream signalling events in melanoma." (PMID 27966454, 2017). "HACE1 influences the ITGB1 expression in melanoma by degrading FN1 via ubiquitination." (PMID 38279122, 2024). "Additionally, MALAT1 has been found to serve as a negative regulator of miR-183 in melanoma cells, thereby controlling the output expression of ITGB1 (integrin subunit beta 1)." (PMID 37373059, 2023). "Furthermore, enforced expression of ITGB1 significantly restored the inhibition of the miR-183 on cell growth and colony formation in melanoma cells." (PMID 27966454, 2017). "Melanoma cells with high levels of MALAT1 showed an increase in ITGB1 expression, which could be markedly inversed by transfection with miR-183." (PMID 27966454, 2017). "Collectively, these data indicated that MALAT1 may act as an endogenous ‘ceRNA’ through binding to miR-183, thus eliminating the miR183-mediated inhibitory effects on the ITGB1 expression and its downstream signalling events in melanoma." (PMID 27966454, 2017). "We then explored that MALAT1 may serve as “sponge ceRNA” to adjust the expression of ITGB1 and tumor growth through inhibiting the expression of miR-183 in melanoma cells, providing a new insight in the therapy of malignant melanoma." (PMID 27966454, 2017). "Melanoma cells express ITGB3 preferentially metastatic to the lungs, whereas melanoma cells expressing ITGB1 preferentially metastasize to lymph nodes." (PMID 38279122, 2024). "Melanoma cells have been shown to produce TIMP1, which helps them overcome apoptosis by building complexes with CD63 and ITGB1." (PMID 38279122, 2024). "In general, our study suggested that miR-183 suppressed cell growth by inhibiting ITGB1 signal pathway and MALAT1 promoted melanoma growth by acting as a ceRNA of miR-183 in melanoma." (PMID 27966454, 2017). "NanoString results suggested that NR4A and ITGB1 genes are highly expressed immune genes in older melanoma patients rather than their younger counterparts with lymph node metastasis." (PMID 33373316, 2020). "We also identified biomarkers, namely, ITGB1, FBN1, and THBS1, secreted by BC cells constituting lesions of all grades as well as the examined adenocarcinomas (colorectal, gastric, hepatocellular, melanoma, non-small cell lung cancer, ovarian, pancreatic, and prostate cancer)." (PMID 36010848, 2022). "Additionally, ITGB1 was over-expressed in melanoma tissues, indicating that ITGB may be involved in melanoma development." (PMID 27966454, 2017).